U8 (U8 small nucleolar RNA )
Synonyms: LOC124900277
Gene: Small nucleolar RNA gene on chromosome 9 (38,147,428 to 38,147,561, forward strand). Ensembl gene ENSG00000200026.
Gene Ontology:
Biological process: RNA processing
Cellular component: nucleolus
Homologues: Orthologues: chimpanzee U8 (99% identical), macaque U8 (93% identical), rabbit U8 (59% identical). Paralogues in human: U8 (87% identical), U8 (84% identical), U8 (83% identical), U8 (81% identical), U8 (79% identical), U8 (77% identical), U8 (76% identical), U8 (75% identical), U8 (67% identical), U8 (66% identical), U8 (64% identical), U8 (63% identical), and 1 more.